IL10 (interleukin 10)
Diseases named in the same sentence as IL10 in open-access papers (continued):
Sharing a sentence is not in itself a finding about the gene and the disease.
Stroke (continued). "Results showed a noticeable increase in hypoxia-inducible factor 1 and IL-10 levels in the DMOG group with a decline in iNOS, TNF-α, and NF-kB levels, implying the anti-inflammatory role of hypoxia-inducible factor 1 activator following stroke." (PMID 34205911, 2021). "Neither the percentage of IL-10-producing monocytes nor the amount of IL-10 expression per cell was altered after stroke of human patients in the stimulated and unstimulated conditions (data not shown)." (PMID 33329318, 2020). "In the Western blot assessment, the protein levels of TNF-α and IL-1β were increased, whereas no change was detected in IL-6 and IL-10 protein levels in the stroke mice at 3 days after stroke." (PMID 32010477, 2020). "The role of IL-10-producing immunosuppressive monocytes after stroke has not been investigated, but monocytes are impaired in oxidative burst and downregulate human leukocyte antigen—DR isotype (HLA-DR) on the cell surface." (PMID 33329318, 2020). "A main component of SCFA-sodium butyrate through its HDAC-inhibiting ability can promote the expression of anti-inflammatory (IL-10) genes and the downstream IL-10/STAT3 pathway in microglia, which can positively promote neurogenesis and axonal growth after a stroke insult." (PMID 33042113, 2020). "In a clinical trial involving 158 healthy volunteers and 158 stroke patients, the levels of various inflammatory factors were elevated in patients with splenic contraction, with significant differences in IFN-γ, IL-6, IL-10, IL-12 and IL-13." (PMID 30700305, 2019). "It is proved that viral overexpression of IL-10 had neuroprotective effects after cerebral ischemia and TGF-β had anti-inflammatory effects by inhibiting excessive neuroinflammation during the subacute phase of stroke." (PMID 31117961, 2019). "Previous reports characterized an acute immune response to ischemic stroke by profiling certain cytokines and chemokines (e.g., IL-1α and β, IL-6, IL-8, IL-9, IL-10, IL-12, IL-18, TNFα and soluble TNF-receptors p55, p75 and GRO-α) in the sera or cerebrospinal fluid of stroke patients." (PMID 31164999, 2019). "The different effects of these cell types on the interleukin (IL)-10, interferon (IFN), and cholinergic anti-inflammatory pathways in the spleen after stroke may promote the development of new cell therapy targets and strategies." (PMID 30700305, 2019). "RIC alone without subsequent stroke obviously promoted plasma IL-6 expression without any impact on the concentration of IL-10 and TNF-α." (PMID 30115811, 2018). "Given the anti-inflammatory role of miR-424 in the brain of experimental stroke, we further examined TNF-α, IL-10 and IGF1 levels in plasma and determined whether an association existed between plasma cytokines and miR-424 levels." (PMID 29675290, 2018). "Moreover, plasma TNF-α and IGF-1 levels increased and decreased, respectively, in stroke patients, and miR-424 levels in lymphocytes and neutrophils were both inversely correlated with plasma TNF-α, IL-10, or IGF-1 levels." (PMID 29675290, 2018). "On the other hand, the level of IL‐4 transiently increased at 24 h and then significantly decreased at 3 and 10 days after stroke; no change in IL‐10 levels was observed at each specific time points." (PMID 29131464, 2018). "Serum levels of IL-10 in infected patients were not different from those in uninfected patients on days 3 and 7 after stroke onset (p > 0.05)." (PMID 27682880, 2017). "In addition, stroke severity is closely correlated with decreased TH1/TH2 ratio, increased production of interleukin (IL)-10, with infected stroke patients showing exacerbated production of IL-10." (PMID 28154551, 2017). "Also, 48 hr after stroke, BML‐111 induced a trend toward an increase in the levels of anti‐inflammatory cytokines IL‐10 and IL‐4 with BML‐111 treatment compared to the vehicle (both p = .1)." (PMID 28523230, 2017).
Stroke (continued). "In the Leiden 85-plus study, patients with a history of stroke displayed lower IL-10 production in response to LPS stimulation than subjects without stroke." (PMID 28659854, 2017). "Based on the literature and our previous studies, miR-155 inhibition could potentiate IL-10/STAT-3-mediated AIR, which could significantly contribute to improved post-stroke recovery reported in our previous study." (PMID 27829437, 2016). "SAI patients had significantly higher IL-6 (Std.MD 2.35; 95%CI 0.82–3.89; P=0.003) and IL-10 (Std.MD 1.08; 95%CI 0.09–2.06; P=0.03) levels compared to stroke patients without infection within 48h after stroke onset." (PMID 27409177, 2016). "On one hand, Treg depletion using CD25-specific monoclonal antibodies resulted in exacerbated long-term brain damage and worsened functional outcome in experimental stroke, potentially due to the lack of IL-10 production." (PMID 26742037, 2016). "SAI patients had significantly higher IL-6 and IL-10 levels and lower HLA-DR levels than no-infection patients within 48h after stroke onset." (PMID 27409177, 2016). "The production of IFN-γ by TH1 cells, proliferation of T cells and cytokine responses, TNF-α production by macrophages and cytokine production by monocytes are all inhibited by IL-10 to further emphasize its role in the immune shift toward a TH2 response and immune suppression after stroke." (PMID 26742037, 2016). "Neither microglia nor brain-recruited monocytes expressed detectable levels of the anti-inflammatory cytokines IL-4 and IL-10 after stroke (data not shown)." (PMID 26022493, 2015). "Our data show that levels of the pro- and anti-inflammatory markers IL-6, CRP and IL-10 differ as early as at 6 h after stroke onset between patients with and without post-stroke infection." (PMID 25613713, 2015). "We hypothesized that early levels of the inflammatory and anti-inflammatory markers LBP, IL-10, IL-6 and CRP are biomarker candidates for the prediction of post-stroke infections in acute ischemic stroke patients." (PMID 25613713, 2015). "The negligible antiinflammatory cytokine IL-10 mRNA seen in our study is similar to that of previous reports in which no expression was seen at day 14 after stroke." (PMID 24690461, 2014). "In an experimental stroke model, intranasal BDNF was shown to modulate local inflammation and protect against cerebral ischemia by upregulating anti-inflammatory cytokine IL-10, down-regulating the pro-inflammatory cytokine TNF-α, and in turn increasing the DNA-binding activity of NFKB." (PMID 23912236, 2013). "Because the anti-inflammatory cytokines, IL-10 and TGF-β, are produced by microglial cells for neuroprotection after traumatic injury or stroke, we examined the secretion of these cytokines using T. gondii-infected Tg2576 mouse brain tissues and BV2 cells (a microglial cell line)." (PMID 22470449, 2012). "IL10 expression remained undetectable by qtPCR analysis, suggesting that IL10 mRNA is not present at these timepoints in the brain following stroke." (PMID 21999375, 2011). "A strong trend towards an effect of stroke depending on the genotype on the levels of IL-10 in the non-infarct region also was obtained (p = 0.05)." (PMID 21714902, 2011). "MBL-low patients showed a cytokine profile after stroke characterized by a greater increase of IL-10, a lower rise of IL-6, and no significant changes of TNF-α compared to patients with MBL-sufficient genotypes." (PMID 20140243, 2010). "Mice with no functioning Treg cells that were injected with IL-10 on the first day following a stroke had markedly less brain damage than mice that did not receive IL-10." (PMID 19919699, 2009). "IL-10 levels can rise within the first few hours after stroke, although the increase may not be as immediate as other pro-inflammatory cytokines like IL-6 or TNF-α." (PMID 40142325, 2025).
Stroke (continued). "Further, the KG diet upregulated the HIF-1α and interleukin (IL)-10 expression and inhibited thioredoxin-interacting protein (TXNIP), NOD-like receptor family pyrin domain-containing 3 (NLRP3) inflammasome activation and pro-inflammatory cytokine expression compared to SD-fed mice after stroke." (PMID 40272769, 2025). "In the early post-stroke phase, Tregs act on peripheral leucocytes to inhibit the production of matrix metalloproteinase-9 (MMP-9) by neutrophils, thereby protecting the blood–brain barrier, and prevent the activation of effector T cells by secreting anti-inflammatory IL-10 and TGF-β." (PMID 35008440, 2021). "Regarding the potent and pleiotropic immunosuppressive properties of IL-10 on the systemic immune compartment, IL-10 itself might not represent an ideal therapeutic target in stroke." (PMID 34772416, 2021). "The number of mammalian achaete-scute homolog 1 (MASH1)-expressing type C cells was decreased by the anti-IL-10 antibody, while GFAP+/Nestin+ cells were increased at 4 days after stroke, suggesting that an IL-10-mediated neuroprotective effect may facilitate the proliferation of NSCs in the SVZ." (PMID 34975872, 2021). "Importantly, depleting microglia induced a significant increase in the mRNA expression level of anti-inflammatory factors TGF-β1, Arg1, IL-10, IL-4, and Ym1 as well as a significant decline of pro-inflammatory factors TNF-α, iNOS, and IL-1β 3 days after stroke." (PMID 33757565, 2021). "In order to explore the roles of astrocytes in post-stroke inflammation, the levels of inflammatory factors were detected in primary astrocytes at 0 h, 6 h, 12 h, 24 h, and 48 h after 6-h OGD, including TNF-α, IL-6, IL-10, inducible nitric oxide synthase (iNOS), IL-1β, and CXCL10." (PMID 31426811, 2019). "In stroke patients, increased cerebrospinal fluid and/or circulating IL-1β, IL-6, IL-10, and CXCL-1 (CINC-1/IL-8), monocyte chemoattractant protein-1, and TNF-α concentrations have been reported, and IL-6 in particular identified as a predictor of stroke outcome." (PMID 21714902, 2011). "The simulation of IL-10 bolus and TNF-α blockade exemplifies how predictive modeling may anticipate unintended immunological trade-offs, information that is critical given the failure of some clinical anti-cytokine therapies to demonstrate efficacy in stroke trials." (PMID 41557608, 2026). "To examine whether the protective effect of HIF-1α after stroke is achieved by modulating inflammation, we evaluated the expression levels and mRNA of pro-inflammatory cytokines (iNOS, TNF-α, NF-κB and p-IκBα/IκBα), and anti-inflammatory cytokines (IL-10) in the ischemic brain." (PMID 34205911, 2021). "Thus, the relationship between IL-10, IL-10 cytokine family, and stroke prognosis could not be performed." (PMID 34336007, 2021). "We could not obtain the change in serum IL-10 concentration after the onset of stroke patients." (PMID 34336007, 2021). "However, expression of Il10 or Tnfα at 24 h post-stroke remained unchanged (data not shown)." (PMID 33568697, 2021). "Although the change in IL-10 with clenbuterol at 4 h after stroke is not significant, this data is consistent with previous reports that stimulation of β2-adrenergic receptors with clenbuterol or norepinephrine induces IL-10 expression and suppresses TNFα expression." (PMID 31138227, 2019). "Furthermore, we observed a trend towards significantly higher IL‐10 and IL‐4 expression at 48 hr, indicating that BML‐111 may be maximally effective at reducing pro‐inflammatory cytokines and increasing anti‐inflammatory cytokines 48 hr after stroke." (PMID 28523230, 2017). "The model explicitly incorporates nonlinear feedback (IL-10 suppression of TNF-α/IL-6), cross-activation (NF-κB-mediated TNF-α/IL-6 synergy), and empirical parameterization from clinical stroke data." (PMID 41557608, 2026).
Stroke (continued). "Silymarin raised cortical TNFα, IL4, IL10, IGF1, BDNF, and CX3CL1 levels in the HFD group with stroke, while the striatum did not present relevant differences." (PMID 39624169, 2024). "Thus, the influence of other factors on IL-10 and stroke prognosis could not be excluded." (PMID 34336007, 2021). "T lymphocytes of stroke patients produced IFN-γ and TNF-α and responded to MBP peptides by increasing their production of TNF-α and IL-10 at admission, but not at later time points." (PMID 32719588, 2020). "Compared to stroke, OGV a.s. significantly reduced the pro-inflammatory marker IL-6 by 49%, but had no influence on IL-10 levels." (PMID 27902774, 2016). "In addition, another study demonstrated that adoptive transfer of IL-10-producing B cells into the stroke mice could increase the expression of PD-1 in peripheral CD4+ T-cells, suggesting that PD-1/PD-L1 interaction might also be important in regulatory B cell-provided neuroprotection after stroke." (PMID 25232304, 2014). "Stroke patients with metabolic syndrome had increased plasma levels of the proinflammatory cytokines CRP, IL-6 and TNF-α but decreased levels of the anti-inflammatory cytokine IL-10 compared to stroke patients without metabolic syndrome and nonstroke patients." (PMID 37587512, 2023). "Nevertheless, this study showed that stroke outcome could not be differentiated by the serum levels of TMAO, IL-17, or IL-10." (PMID 35153980, 2021). "Considering the continuous increase in stroke morbidity/mortality and the lack of non-invasive biomarkers of the disease, our study aimed to evaluate TNF-α, IL-6, and IL-10 levels in the non-stimulated (NWS) and stimulated (SWS) whole saliva of stroke patients." (PMID 34433866, 2021). "In the past, there have been many attempts to treat stroke by intervention on the peripheral immune system, mainly through the intervention of cytokine receptors, such as TNF-α, IL-1, IL-6 and IL-10, while most of the attempts failed to be translated into clinical application." (PMID 34876161, 2021). "While computational models have explored isolated aspects of post-stroke inflammation, such as TNF-α-mediated microglial activation or IL-6’s dual neurotoxic/neuroprotective roles, no study has yet integrated TNF-α, IL-6, and IL-10 into a unified mathematical model." (PMID 41557608, 2026). "Moreover, there were significant negative correlations between ovarian IL-6 and ovarian IL-10 expression and 2d ART performance, suggesting that ovarian cytokine expression may directly affect stroke outcomes." (PMID 37408003, 2023).
lupus (289 papers, 2006 to 2026). "In this study, we identified Hspa13 as a novel positive regulator of IL‐10 producing Bregs and demonstrated that Hspa13 deficiency in MZ B cells contributed to lupus disease pathology by reducing Tregs." (PMID 39737854, 2025). "In vitro stimulation either with P. distasonis or via TLR9 allowed for the differentiation of IL-10 producing B cells which, in vivo, differentially accumulated in the Peyer ́s patches of Bank1-deficient lupus mice." (PMID 40761803, 2025). "Dysregulated IL‐10 producing regulatory B cells (Bregs) are associated with the progression of systemic lupus erythematosus." (PMID 39737854, 2025). "A single nucleotide polymorphism rs3024505(C/T), located downstream of the IL10 gene, is associated with several aggressive inflammatory diseases, including systemic lupus erythematosus, Sjögren’s syndrome, Crohn’s disease, and ulcerative colitis." (PMID 39337678, 2024). "The IL-10 cytokine is specifically known for its suppressive function; however, in lupus, IL-10 is pathogenic, promoting direct differentiation of activated B cells into plasma cells." (PMID 39337564, 2024). "IL-17 deficiency led to an increased number of CD19+IL-10+Breg in the spleen of a murine model of lupus." (PMID 37771588, 2023). "The deficiency of IL-17 led to an increased number of CD19+IL-10+Breg in the spleen of a murine model of lupus." (PMID 37771588, 2023). "Decreased IL-10R1 expression on peripheral T cells in lupus patients correlates with heightened T cell activity, suggesting that reduced receptor expression is associated with reduced IL-10 function." (PMID 35428872, 2022). "They found that IL-10 depletion was closely related to severe and early-onset lupus and was also associated with IFN-γ production and an increased serum concentration of anti-dsDNA autoantibodies, similar to our observations in patients with TAILS." (PMID 35733860, 2022). "In another study, mice treated with IL-35 were characterized by significantly alleviated lupus flare and nephritis, which was associated with the expansion of Tregs and IL-10-producing Bregs." (PMID 36555351, 2022). "A changed base in rs3122605-G upregulated IL10 gene expression and increased the risk of systemic lupus erythematosus in European Americans." (PMID 34868229, 2021). "We found a disease-associated increase in Ly6Clow patrolling monocytes that expressed high levels of TLR7 and had upregulated expression of lupus-associated IL-10, CD115, CD31, and TNFSF15 in NZBWF1 mice." (PMID 34868046, 2021). "In the present study, we conducted a prophylactic co-vaccination with DNA plasmids encoding D183-119, D2, B ́/B, and B ́/BCOOH epitopes and IL-10 or IFN-γ with a follow-up period of 6 months after lupus induced by pristane." (PMID 34705865, 2021). "In this study, we aimed to evaluate the induction of antigen-specific tolerance by a prophylactic co-vaccination with DNA encoding Sm antigens along with IL-10 or IFN-γ in a pristane-induced murine model of lupus." (PMID 34705865, 2021). "Transcriptome and FACS analyses revealed increased expression of lupus-associated molecules such as IL-10, which promotes nephritis, in monocytes that accumulated in the spleen." (PMID 34868046, 2021). "pSTAT3 also promotes the expression of another cytokine in lupus T cells that has been associated with SLE: IL-10." (PMID 32503684, 2020). "It is known that both overexpression (e.g., in systemic lupus erythematosus or tuberculosis) and deficiency (e.g., in psoriasis or rheumatoid arthritis) of IL-10 can be associated with pathological processes." (PMID 32630798, 2020). "The importance of IL-10 in restricting lupus has been shown in IL-10-deficient mice which developed exacerbated glomerulonephritis and immune complex deposition after lupus was induced by dendritic cells that had ingested necrotic cells." (PMID 31297111, 2019).